ALDH2 (aldehyde dehydrogenase 2 family member)
Diseases named in the same sentence as ALDH2 in open-access papers (continued):
Sharing a sentence is not in itself a finding about the gene and the disease.
lung carcinoma (33 papers, 2006 to 2025). "Other DEPs including aldo-keto reductase family 1 member B1 (AKR1B1), cyclin-dependent kinase 2 (CDK2), death associate protein kinase-1 (DAPK1), peroxiredoxin-1 (PRDX1) and aldehyde dehydrogenase mitochondrial (ALDH2) are associated with lung cancer." (PMID 40088196, 2025). "Downreglation of ALDH2 has also been reported in lung cancer, and ALDH2 interacting with alcohol drinking are risk factors of stomach cancer." (PMID 25408144, 2014). "Next, we examined the roles of Aldh2-deficiency in lung cancer cells." (PMID 38292172, 2024). "This may explain why ALDH2-deficiency promotes the metastatic features in lung cancer cells, whereas Aldh2-KO is toxic to BASCs, especially with ethanol treatment." (PMID 38292172, 2024). "The expression of ALDH2 in human lung cancer is significantly down-regulated, and the overexpression of ALDH2 causes an inhibitory effect on the proliferation and colony formation of lung cancer cells, while the silencing of ALDH2 can reverse the tumor-suppressive effects." (PMID 38378847, 2024). "It was found that reduced ALDH2 levels impair the pathway of detoxification of acetaldehyde to nontoxic acetic acid and proved how it caused DNA damage and promoted the growth and development of lung cancer." (PMID 35646120, 2022). "Thus, ALDH2 deficiency promotes tumor progression in both mouse and human lung cancer cells." (PMID 38292172, 2024). "It is plausible that in addition to potential interactions between ALDH2‐rs671 genotype and alcohol in lung cancer risk, these genotypes may interact with other exogenous sources of aldehyde (eg, air pollution) which could influence risk of lung cancer." (PMID 35048370, 2022). "The proteins such as AKR1B1, CDK2, DAPK1, PRDX1 and ALDH2 show potential as biomarkers or therapeutic targets for radon-related lung cancer after further validation." (PMID 40088196, 2025). "Another two sample study on Asian population using ALDH2-rs671 and ADH1B-rs1229984, an increase of 280 g/week in alcohol consumption was associated with a decreased risk of lung cancer in men [HR = 0.81 (0.67–0.98)]." (PMID 39574800, 2024). "Downregulation of ALDH2 has been demonstrated to improve the efficacy of anthracyclines in renal cell carcinoma via von Hippel-Lindau (VHL) deficiency 13 and to sensitize lung cancers to paclitaxel by reducing cancer stemness." (PMID 37476181, 2023). "Our findings suggest that ALDH2 plays a role as a pro-oncogene in the process of PTX resistance in lung cancer." (PMID 35477569, 2022). "Collectively, the study unveils the molecular role of SNHG16 in regulating the development of lung cancer by interacting with ALDH2." (PMID 35646120, 2022). "The study highlights the prognostic and therapeutic role of SNHG16 in lung cancer and advocates the targeting of SNHG16/ALDH2 axis as potential and novel anticancer strategy against the devastating malignancy of human lung cancer." (PMID 35646120, 2022). "Low expression of ALDH2 was associated with high level of XRCC1 and was indicative of poorer 5-year overall survival in liver and lung cancer patients." (PMID 35330099, 2022). "Bioinformatic analysis revealed that SNHG16 interacted with ALDH2 to exert its effects in human lung cancer cells." (PMID 35646120, 2022). "For further confirmation, we evaluated the expression of ALDH2 in lung cancer tissues and cell lines by qRT-PCR." (PMID 35646120, 2022). "Taken together, the results of current study suggest prognostic and therapeutic utility of lncRNA-SNHG16 and its down-stream target ALDH2 against human lung cancer." (PMID 35646120, 2022). "The role of ALDH2 in tumorigenesis and progression of other cancers such as colorectal cancer, gastric cancer, liver cancer, pancreatic cancer and lung cancer has also been reviewed recently." (PMID 35330099, 2022). "It was found that the expression pattern of ALDH2 in lung cancer tissues was also found to be downregulated in human ALDH2 in lung cancer cell lines." (PMID 35646120, 2022).
lung carcinoma (continued). "The results thus confirmed the modulation of growth regulatory effects of SNHG16 in lung cancer through ALDH2 posttranscriptional downregulation." (PMID 35646120, 2022). "The expression of ALDH2 was found to be significantly (P < 0.05) suppressed in human lung cancer tissues and cell lines." (PMID 35646120, 2022). "The study made it lucid that repression of ALDH2 at posttranscriptional level by SNHG16 was responsible for exerting the growth regulatory role of latter in lung cancer." (PMID 35646120, 2022). "The lung cancer cell viabilities and colony formation was found to be significantly (P < 0.05) lower under ALDH2 overexpression." (PMID 35646120, 2022). "Among male drinkers, the risks associated with higher alcohol consumption were greater among ALDH2‐rs671 AG than GG carriers for head and neck, oesophageal and lung cancers (Pinteraction < .02)." (PMID 35048370, 2022). "As for ALDH2, Li found that restoring the expression of ALDH2 in lung adenocarcinoma can inhibit the migration of lung cancer cells, which was consistent with our findings." (PMID 34670872, 2021). "In future studies, we will detect the DNA methylation level of ALDH2 in the human lung cancer samples and establish a BM model to further analyze the effects and mechanisms of ALDH2 on BM in lung cancer and EMT in vivo." (PMID 32850324, 2020). "The high methylation rates for CpG island 3 in the promoter of ALDH2 result in the downregulation of ALDH2 in lung cancer cell lines." (PMID 32850324, 2020). "Further analysis on ALDH2, ALDH3a1, FBP1, PGD, TALDO1, and TPI1 as biomarkers on the evolution of IPF patients, their association with PJ infection, and their lung cancer risk could be relevant." (PMID 39997396, 2025). "Similarly, a complex of disulfiram with copper reduced ALDH2 expression in lung cancer A549 cells and enhanced chemosensitivity to taxol." (PMID 38612911, 2024). "However, despite the importance of ALDH2 in lung cancer, the epigenetic profile and signaling pathways that resulted in ALDH2 abnormal expression in LUAD remain little understood." (PMID 36936815, 2023). "Pathway analysis showed that the TGFβ pathway, RAF pathway, EMT pathway and so on were significantly enriched (P < 0.05), which suggests that these pathways may be involved in ALDH2-mediated PTX resistance in lung cancer." (PMID 35477569, 2022). "Similar to our observations, overexpression of ALDH2 resulted in higher cell proliferation rate, higher clone formation rate, and resistance to 4-hydroperoxycyclophosphamide and doxorubicin in leukemia and lung cancer cell lines." (PMID 35477569, 2022). "We hypothesized that the upregulation of ALDH2 was significantly correlated with PTX resistance in lung cancer." (PMID 35477569, 2022). "The repression of ALDH2 in lung cancer and its tumor promoting role has been worked out previously." (PMID 35646120, 2022). "IHC analysis also showed considerable downregulation of ALDH2 in lung cancer tissues." (PMID 35646120, 2022). "Hence, the present research work is an extension to the established research results about the role of ALDH2 in lung cancer and disclosed the mechanism accounting for its repression in lung cancer to promote the advancement of this deadly disease." (PMID 35646120, 2022). "For example, overexpression of ALDH2 resulted in higher cell proliferation rate, higher clone formation rate, and resistance to 4-hydroperoxycyclophosphamide and doxorubicin in leukemia and lung cancer cell lines." (PMID 35477569, 2022). "However, overexpression of SNHG16 in A549 lung cancer cells increased the protein concentration of ALDH2 in lung cancer cells." (PMID 35646120, 2022). "Similar significant interactions between alcohol and ALDH2‐rs671 were also observed for site‐specific cancers, especially oesophageal cancer (Pinteraction < .0001) and head and neck cancer (Pinteraction < .01) and less so for lung cancer (Pinteraction = .016)." (PMID 35048370, 2022).
lung carcinoma (continued). "In order to further explore whether ALDH2 is involved in the PTX resistance process in lung cancer, we used the Cancer Cell Line Encyclopedia (CCLE) and Genomics of Drug Sensitivity in Cancer (GDSC) database to analyze the relationship between the two." (PMID 35477569, 2022). "The expression of ALDH2 was also downregulated in human lung cancer cell lines." (PMID 35646120, 2022). "Next, we dissected the role of ALDH2 in lung cancer resistance to PTX." (PMID 35477569, 2022). "In lung cancer, overexpression of ALDH2 inhibits the malignant characteristics of lung adenocarcinoma cells, such as proliferation, stemness, and migration, while knocking down ALDH2 increases these characteristics." (PMID 34670872, 2021). "Moreover, XRCC1 interacts with ALDH2 and predicts poor OS in patients with lung cancer and liver cancer." (PMID 32258128, 2020). "Methylated ALDH2 greatly increases the probability of BM in lung cancer patients." (PMID 32850324, 2020). "We thus conclude that XRCC1 mRNA levels along with ALDH2 mRNA levels may be used for stratification in order to predict the 5-year overall survival rate in liver and lung cancer patients and to refine their treatment strategy." (PMID 30088263, 2018). "We focused on ALDH1A1, ALDH2 and ALDH3A1 expression among the various isoforms because ALDH1A1 and ALDH3A1 have been shown to be markers of resistance to cyclophosphamide in breast and lung cancer cells and because ALDH2 is a major detoxifying enzyme for reactive aldehydes." (PMID 28881734, 2017). "However, more research is needed to determine whether ALDH2 is a lung cancer stem biomarker that can be used to target LUAD treatment." (PMID 36936815, 2023). "Additionally, SNH16 was found to be negatively correlated (r = −0.812) with ALDH2 expression, and the upregulation of SNH16 was manifested as transcriptional repression of ALDH2 suggesting the modulation of molecular role of SNH16 through ALDH2 targeting in lung cancer." (PMID 35646120, 2022). "It is possible that the observed ALDH2‐rs671‐alcohol interactions might be partly related to acetaldehyde from smoking rather than from alcohol consumption alone, especially for lung cancer for which no causality of alcohol has been inferred by genotypic associations." (PMID 35048370, 2022). "In CKB, there were generally lower risks of liver, colorectal and stomach cancers comparing ALDH2‐rs671 AA vs GG genotype among men, but precision was low due to the small numbers of AA carriers, and no clear genotypic associations were observed for lung cancer." (PMID 35048370, 2022). "However, no independent risk factor is identified between lung cancer and ALDH2 polymorphism." (PMID 36523602, 2022). "To do so, we selected two cancer-derived cell lines, i.e., H1299, a lung cancer-derived cell line with a low ALDH2 expression and JHH4, a liver cancer-derived cell line with a high ALDH2 expression." (PMID 30088263, 2018). "It was shown that overexpression of ALDH2 can inhibit the invasion and migration of lung adenocarcinoma cells, and the expression of ALDH2 is related to the overall survival rate of lung cancer and HCC patients: low expression of ALDH2 indicates a low 5-year survival rate for patients." (PMID 39132147, 2024). "ALDH2 has been identified as a CSC marker in liver and lung cancers." (PMID 38612911, 2024). "Similarly, inhibition of ALDH1A2 and ALDH2 by DEAB showed an obvious concentration dependence in K562 leukaemia cells and H1299 lung cancer cells." (PMID 36651035, 2023). "However, the role of lncRNA SNHG16 in lung cancer via modulation of ALDH2 expression has not been studied and was thus the objective of the present study." (PMID 35646120, 2022). "Moreover, we observed, particularly in breast, brain and lung cancer cohorts, a strong negative correlation between ALDH2 and BRIP1." (PMID 34454516, 2021).
lung carcinoma (continued). "In this study, we found that ALDH2 expression could be induced by inhibiting DNMT3A expression, which indicated that ALDH2 can be regulated by DNMT3A, greatly reducing the probability of BM in lung cancer patients." (PMID 32850324, 2020).
ischemic stroke (31 papers, 2016 to 2026). A stroke disorder caused by obstruction of blood flow to the brain, due to thrombotic (local blood clot formation) or embolic (due to a blood clot or other material traveling from another site) event. "Beyond alcohol intolerance, ALDH2 polymorphism has been associated with several cardiovascular conditions, including coronary artery disease and ischemic stroke." (PMID 41324337, 2026). "In East Asian men, heavy alcohol consumption among ALDH2*2 carriers is associated with earlier ischemic stroke onset, suggesting a gene–environment interaction." (PMID 41324337, 2026). "Our prior work in a large Taiwanese cohort identified the ALDH2*2/*2 genotype as an independent risk factor for ischemic stroke in men, suggesting underlying genetic vulnerability." (PMID 41324337, 2026). "A Chinese study found that the ALDH2 rs10744777 (CT/TT) genotypes were independent risk factors for ischemic stroke in males, and the ALDH2 rs886205 GA genotype was related to poorer prognosis exclusively in male patients with ischemic stroke." (PMID 39290715, 2024). "Consistently, a recent multi-ancestry meta-analysis reported the association between the ALDH2 locus and ischemic stroke with significant sex heterogeneity." (PMID 39290715, 2024). "One of those variants is ALDH2 rs10744777 which is reported to be associated with the risk of ischemic stroke among European and East Asian populations." (PMID 37943872, 2023). "Several studies have identified the ALDH2*2 allele as an independent risk factor for ischemic stroke and cerebral infarction in the Chinese population." (PMID 37006480, 2023). "Significant associations at MTHFR and ALDH2 robustly confirm deleterious effects of genetically elevated homocysteine and alcohol intake, respectively, on ischemic stroke." (PMID 36193932, 2022). "In a Taiwanese study with 914 participants, homozygous ALDH2 deficiency (ALDH2*2/*2) was found to be an independent risk factor for ischemic stroke, although only for men." (PMID 36010652, 2022). "In conclusion, this large‐scale targeted sequencing study implicated 3 loci—FADS1‐FADS2, MTHFR, and ALDH2—in ischemic stroke." (PMID 36193932, 2022). "We are also among the first to describe an interaction of the ALDH2 rs671 variant and alcohol intake on ischemic stroke, bolstering support for the potentially harmful etiologic effects of excessive alcohol consumption on this condition." (PMID 36193932, 2022). "These variants, likely reflecting the association of the functional ALDH2 rs671 missense variant, conferred 0.54‐fold decreased odds of ischemic stroke among drinkers in meta‐analyses, with substantially attenuated associations among nondrinkers." (PMID 36193932, 2022). "Several studies have confirmed that the common functional single nucleotide polymorphism (SNP) in exon 12 of ALDH2 is a risk indicator for ischemic stroke." (PMID 34257742, 2021). "To test the possible association between ALDH2 polymorphisms and cognitive impairment in patients with ischemic stroke, we therefore used two different MoCA cutoff scores to investigate interaction effects." (PMID 34257742, 2021). "Previous studies have revealed that ALDH2 polymorphisms are closely related to the incidence of ischemic stroke." (PMID 34257742, 2021). "To test the possible association of ALDH2 polymorphism and alcohol consumption with cognitive impairment, we assessed the separate effects of ALDH2 polymorphism and alcohol consumption on cognitive impairment in ischemic stroke patients." (PMID 34257742, 2021). "To assess the associations of ALDH2 polymorphisms and alcohol consumption with cognitive impairment after ischemic stroke, we performed binary logistic regression analysis with odds ratios." (PMID 34257742, 2021). "Although previous studies have evaluated the interaction between alcohol drinking and ADH1B and ALDH2 variants, they mainly focused on ischemic stroke and ALDH2 rs671." (PMID 34051793, 2021).